TMEM176B (transmembrane protein 176B)
Description:
May play a role in the process of maturation of dendritic cells. Required for the development of cerebellar granule cells (By similarity).
Synonyms: LR8; MS4B2
Tractability: Antibody: UniProt predicts a signal peptide or a membrane-spanning region; the Human Protein Atlas places it where antibodies can reach. PROTAC: its protein half-life has been measured.
Gene: Protein-coding gene on chromosome 7 (150,790,382 to 150,803,404, reverse strand). Ensembl gene ENSG00000106565.
Subcellular location: Nucleus membrane
Subcellular location (Human Protein Atlas): Golgi apparatus; Nucleoplasm; Plasma membrane
Gene Ontology:
Molecular function: protein binding
Biological process: animal organ morphogenesis; negative regulation of dendritic cell differentiation
Cellular component: membrane; nuclear membrane
Genetic constraint (gnomAD): Loss-of-function variants: 28 observed, 30.57 expected, observed/expected ratio (o/e) 0.92, 90% interval 0.68 to 1.26. The upper end of that interval is the gene's LOEUF score, 1.26, which puts it in group 5 of 6, group 1 being the genes least tolerant of losing a copy. Missense variants: 349 observed, 343.6 expected, observed/expected ratio (o/e) 1.02, 90% interval 0.93 to 1.11. Synonymous variants: 123 observed, 136.34 expected, observed/expected ratio (o/e) 0.9, 90% interval 0.78 to 1.05.
Homologues: Orthologues: chimpanzee TMEM176B (99% identical), macaque TMEM176B (91% identical), dog TMEM176B (66% identical), rabbit TMEM176B (57% identical), pig TMEM176B (54% identical), mouse Tmem176b (52% identical), rat Tmem176b (51% identical). Paralogues in human: TMEM176A (28% identical).
Diseases named in the same sentence as TMEM176B in open-access papers:
TMEM176B is named in the same sentence as 43 diseases in open-access papers, as found by Europe PMC text mining. Sharing a sentence is not in itself a finding about the gene and the disease. The quoted sentences say what the papers report.
breast carcinoma (5 papers, 2015 to 2025). "Abnormal DNA methylation of CpG islands in human TMEM176A and TMEM176B is associated with breast cancer development." (PMID 39717774, 2024). "Additionally, TMEM176B has been implicated in the development of various cancers, including breast cancer and colorectal cancer, where its expression levels correlate with disease progression and patient outcomes." (PMID 39001509, 2024). "Importantly, an altered expression of TMEM176B has been found in a number of cancer types, while abnormal methylation of the CpG islands associated with TMEM176B was reported in breast cancers." (PMID 34943938, 2021). "Recent research suggests a rise in TMEM176B expression within breast cancer, notably in triple-negative breast cancer." (PMID 39001509, 2024). "Treating MDA-MB-231 cells with TMEM176B antibodies also reduces cell proliferation, suggesting the potential of this gene as a target for breast cancer therapy." (PMID 39001509, 2024). "Overall, our results suggest that TMEM176B expression in breast cancer cells regulates key signaling pathways and genes that contribute to cancer cell growth and progression, and is a potential target for therapeutic antibodies." (PMID 34943938, 2021). "To evaluate the role of TMEM176B in human breast cancer, we assessed the expression of TMEM176B in different breast cancer subtypes in the Molecular Taxonomy of Breast Cancer International Consortium and The Cancer Genome Atlas (TCGA) datasets." (PMID 34943938, 2021). "In this study, we aimed to understand the function of the proposed ion channel TMEM176B in breast cancer." (PMID 34943938, 2021). "To determine if silencing TMEM176B affected the growth of human breast cancer xenografts, we injected control and TMEM176B-silenced cells into the fourth mammary fat pad of immunodeficient female Rag1−/− mice." (PMID 34943938, 2021). "We found that TMEM176B expression on breast cancer cells was important for cell proliferation and migration, AKT/mTOR signaling, and the regulation of a number of genes involved in angiogenesis, KRAS signaling, EMT, and estrogen and interferon responses." (PMID 34943938, 2021). "We generated breast cancer cell lines with overexpressed and silenced TMEM176B, and a therapeutic antibody targeting TMEM176B." (PMID 34943938, 2021). "Our interest in TMEM176B began when we identified it as the most upregulated gene in a c-Myc/VEGFA-expressing murine breast cancer cell line (Mvt1) sorted by flow cytometry based on the positive expression of the sialoglycoprotein CD24." (PMID 34943938, 2021). "TMEM176A and TMEM176B, two transmembrane proteins that were recently found to be elevated in breast cancer and other human malignancies were significantly elevated in the CD24+ cells." (PMID 26040280, 2015). "Similarly, in breast cancer, TMEM176B promotes proliferation and migration by activating the PI3K/Akt signaling pathway." (PMID 40108613, 2025). "Moreover, a recent study indicated an increase in TMEM176B expression in breast cancer and a reduction in TMEM176B expression suppressed tumour growth in vitro and in vivo." (PMID 39001509, 2024). "Additionally, the expression levels of TMEM176A and TMEM176B differ significantly between cancerous and normal tissues in breast cancer, lymphoma, skin cancer, and liver cancer, suggesting their potential as diagnostic markers for tumors." (PMID 39717774, 2024). "Thus far, the abnormal expression of TMEM176B has been noted in gastric, prostate and breast cancer." (PMID 39001509, 2024). "To understand the role of TMEM176B in tumor growth, we silenced TMEM176B in the human basal-like MDA-MB-231 breast cancer cell line using two shRNA constructs (176Bsh1 and 176Bsh2) and confirmed the gene silencing by RNA and protein analysis." (PMID 34943938, 2021).
breast carcinoma (continued). "We found TMEM176B amplified in 6.5%, showing a copy number gain in 20.1% of basal-like breast cancers, which have significant cross-over with TNBC compared with other breast cancer subtypes in the METABRIC dataset." (PMID 34943938, 2021). "TMEM176A and TMEM176B are closely related members of the MS4 transmembrane protein family, and have previously been found to physically interact, and their mRNA expression is highly correlated in the TCGA (R2 = 0.88) and METABRIC (R2 = 0.78) human breast cancer datasets." (PMID 34943938, 2021).
gastric cancer (5 papers, 2023 to 2025). A primary or metastatic malignant neoplasm involving the stomach. "The present study aimed to investigate the expression level, biological function, and underlying mechanism of transmembrane protein 176B (TMEM176B) in gastric cancer (GC)." (PMID 38438907, 2024). "Studies have shown that TMEM176B can regulate the growth of gastric cancer and triple-negative breast cancer by regulating the PI3K-Akt-mTOR pathway." (PMID 40108613, 2025). "TMEM176B is known to significantly promote the progression of gastric cancer, whereas it has a favorable prognosis for melanoma patients." (PMID 40108613, 2025). "The bioinformatics and PCR analyses showed that TMEM176B mRNA expression was higher in the gastric cancer cell lines than in GES1." (PMID 38438907, 2024). "The present study aimed to elucidate the molecular mechanisms of TMEM176B and identify novel therapeutic targets and optimize treatment strategies for gastric cancer." (PMID 38438907, 2024). "In gastric cancer patients, TMEM176B expression was observed to be elevated in tumour tissues compared to normal tissues and patients with a high TMEM176B expression exhibited significantly lower survival rates than those with a low expression." (PMID 39001509, 2024). "Recently, studies indicated that TMEM176B is a positive regulator in breast and gastric cancers, and it could be a potential target for treatment." (PMID 39001509, 2024). "TMEM17A and TMEM176B are tumor suppressor genes whose expression is positively correlated with increased T cell infiltration and better overall survival in patients with melanoma or gastric cancer." (PMID 37435077, 2023). "We used colony formation and EdU assays to evaluate the impact of TMEM176B knockdown on GC cell proliferation and found that the proliferation ability of gastric cancer cells was significantly decreased." (PMID 38438907, 2024).
melanoma (4 papers, 2019 to 2023). A malignant, usually aggressive tumor composed of atypical, neoplastic melanocytes. "One study found that silencing TMEM176B on melanoma-associated endothelial cells reduced their migration in vitro." (PMID 34943938, 2021). "Therefore, TMEM176B is a potential diagnostic or prognostic biomarker for melanoma." (PMID 35399535, 2022). "We investigated the role of Tmem176b in a mouse melanoma model and sought to continue to explore the role of Tmem176b in the regulation of CD8+ T cells in the tumor microenvironment." (PMID 35399535, 2022). "Our animal experiments also verified that the T-cell infiltration was significantly inhibited in local melanoma tissue of Tmem176b knockout mice." (PMID 35399535, 2022). "The correlation analysis revealed that there was a statistical difference between TMEM176B and T stage, pathologic stage (p <0.05), and melanoma ulceration, radiation therapy, breslow depth (p <0.001)." (PMID 35399535, 2022). "To validate our hypothesis, we developed melanoma model in Tmem176b knockout mice and revealed that T cell infiltration and effector function were significantly inhibited." (PMID 35399535, 2022). "In addition, the correlation between TMEM176B and tumor immunity and its role in melanoma is less reported." (PMID 35399535, 2022). "Interestingly, TMEM176B was associated with diminished NLRP3 and IL1B expression in macrophages infiltrating human melanoma, suggesting that this ion channel may function as an innate checkpoint signal that hinders immune responses in the tumor microenvironment." (PMID 31085177, 2019). "It is unknown the role of TMEM176B in regulating CD8+ T cells biology and the course of melanoma." (PMID 35399535, 2022).
prostate carcinoma (4 papers, 2021 to 2025). A carcinoma that arises from epithelial cells of the prostate gland. "In contrast, TMEM176B is a negative regulator in prostate cancer where the overexpression of TMEM176B reduces LNCap cell proliferation, invasion and migration." (PMID 39001509, 2024). "Through a series of cellualr experiments, we found that inhibition of ITGB5 or activation of TIMP1 and TMEM176B suppress prostate cancer." (PMID 34109215, 2021). "We found that ITGB5 was significantly higher in prostate cancer compared with BPH cells, and that TMP1 and TMEM176B were significantly low expressed in prostate cancer." (PMID 34109215, 2021). "In contrast, the overexpression of TMEM176B led to decreased proliferation of the androgen-sensitive LNCaP prostate cancer cell line and reduced the growth of NIH3T3 cells transfected with constitutively active H-Ras." (PMID 34943938, 2021). "In this work, we have used CRISPR interference (CRISPRi) and CRISPR activation (CRISPRa) technologies to study the biologocal functions of ITGB5, TIMP1, and TMEM176B in prostate cancer cells." (PMID 34109215, 2021). "In this study, we used CRISPR interference (CRISPRi) and CRISPR activation (CRISPRa) technologies to regulate the transcription of ITGB5, TIMP1, and TMEM176B in prostate cancer cells." (PMID 34109215, 2021). "Although ITGB5, TIMP1, and TMEM176B are abnormally expressed in several cancers, their molecular biological mechanisms in prostate cancer cells are still to be investigated." (PMID 34109215, 2021). "Although these evidences suggest that ITGB5, TIMP1, and TMEM176B may work together to promote the invasion and metastasis of cancer cells, their molecular biological mechanisms in prostate cancer cells are still unclear and require further research." (PMID 34109215, 2021). "This suggests that ITGB5 is a potential proto-oncogene in the prostate cancer LNCap cell line, while TMP1 and TMEM176B are potential tumor suppressor genes." (PMID 34109215, 2021). "We designed different CRISPR transcriptional regulatory systems to silence ITGB5 in prostate cancer cells and activate TIMP1 and TMEM176B at the same time." (PMID 34109215, 2021). "In this study, we found that compared with prostate hyperplasia cells BPH, ITGB5 is significantly higher expressed in prostate cancer cells, and TMP1 and TMEM176B are significantly lower expressed." (PMID 34109215, 2021). "Interestingly, in the androgen-sensitive LNCaP prostate cancer cell line and NIH3T3 cells transfected with constitutively active H-Ras, overexpression of TMEM176B decreased cell proliferation and growth." (PMID 34943938, 2021).
colorectal cancer (3 papers, 2019 to 2025). A primary or metastatic malignant neoplasm that affects the colon or rectum. "In colorectal cancer, higher expression of TMEM176B is associated with lower overall survival rates." (PMID 40108613, 2025). "In addition, TMEM176B expression in the tumor stroma was associated with poor survival in colorectal cancer patients, suggesting a potential role of this ion channel as a prognostic factor." (PMID 31085177, 2019). "TMEM176B also plays an important role in the prognosis of colorectal cancer by enhancing the activation of the NLRP3 inflammasome." (PMID 39001509, 2024).
COVID-19 (3 papers, 2021 to 2023). A disease caused by infection with severe acute respiratory syndrome coronavirus 2. "In critical COVID-19 patients, low monocytic expression of TMEM176B was associated with increased plasmatic active Caspase-1 which also correlated with CD8+ T cell exhaustion." (PMID 36340035, 2022). "In COVID-19 patients, TMEM176B expression in peripheral blood and bronchioalveolar lavages was associated with mild disease." (PMID 36340035, 2022). "Tmem176B has also been associated with an immature state of dendritic cells, suggesting that ENPP2 expression from COVID-19 pDCs, via LPA, delays their maturation." (PMID 34576169, 2021). "Also, inflammasome activation correlated with dysfunctional T cells and low monocytic TMEM176B expression in severe COVID-19." (PMID 37113134, 2023).
lung carcinoma (3 papers, 2023 to 2024). "Recent studies have indeed suggested a role for TMEM176B in various types of cancer, including lung cancer." (PMID 39170226, 2024). "In mouse experimental models, genetic deletion of TMEM176B was associated with controlled tumor progression in EG7 lymphoma, MC38 colon, and LL2 lung cancer." (PMID 39170226, 2024). "This suggests that TMEM176B could play a role in modulating the immune response to tumors, potentially influencing the progression of diseases such as lung cancer." (PMID 39170226, 2024). "This indicates that TMEM176B could have a significant impact on the immune response to lung cancer, potentially influencing disease progression and treatment outcomes." (PMID 39170226, 2024).
triple-negative breast carcinoma (3 papers, 2021 to 2025). An invasive breast carcinoma which is negative for expression of estrogen receptor (ER), progesterone receptor (PR), and human epidermal growth factor receptor 2 (HER2). "Recently, a study suggested that the AKT/mTOR signalling pathway is a major pathway in TMEM176B-dependent signalling in triple-negative breast cancer." (PMID 39001509, 2024).
lung adenocarcinoma (2 papers, 2024 to 2025). A carcinoma that arises from the lung and is characterized by the presence of malignant glandular epithelial cells. "In summary, elevated TMEM176B expression was observed in lung adenocarcinoma, with higher levels associated with poorer prognosis and decreased overall survival." (PMID 39001509, 2024). "Our study indicated that TMEM176B expression was enhanced in lung adenocarcinoma tissues, and it was associated with shorter overall survival (OS)." (PMID 39001509, 2024). "Collectively, these findings indicate that TMEM176B functions as a positive regulator in colon, breast, and lung adenocarcinomas." (PMID 40108613, 2025). "A recent investigation demonstrated that overexpression of TMEM176B promotes EMT through the FGFR/JNK signaling pathway in lung adenocarcinoma." (PMID 40108613, 2025). "Further analysis of staining intensity affirmed elevated TMEM176B expression in lung adenocarcinoma." (PMID 39001509, 2024). "The FGFR1/JNK/Vimentin/Snail signalling cascade emerges as a pivotal pathway governing EMT in lung adenocarcinoma through TMEM176B overexpression, and this suggests that TMEM176B is a potential therapeutic target for lung adenocarcinoma." (PMID 39001509, 2024). "This study aims to investigate the role of TMEM176B in the development of lung adenocarcinoma (LUAD)." (PMID 39001509, 2024). "Nevertheless, it was observed that in lung adenocarcinoma, patients with elevated TMEM176B transcript levels experienced a significantly shorter overall survival (p = 2.4 × 10−5) compared to those with lower transcript levels." (PMID 39001509, 2024). "To explore the signalling pathway in lung adenocarcinoma cells after TMEM176B overexpression, we chose candidates from our scRNA-seq and proteomics results and literature reviews." (PMID 39001509, 2024). "In this study, we used single-cell sequencing, proteomics, Co-IP, and in vivo and in vitro experimental models to investigate the role of TMEM176B in lung adenocarcinoma development." (PMID 39001509, 2024). "In this present study, the analysis of TMEM176B protein expression in lung adenocarcinoma was examined with relevant clinical and pathological data." (PMID 39001509, 2024). "Our study demonstrated the important role played by TMEM176B in lung adenocarcinoma cells." (PMID 39001509, 2024). "Moreover, the overexpression of TMEM176B led to increased cell proliferation, invasion, migration, and the adhesion of lung adenocarcinoma cells in vitro, and it also promoted tumour growth in vivo." (PMID 39001509, 2024). "Overall, our study suggests TMEM176B could be a potential therapeutic target in lung adenocarcinoma." (PMID 39001509, 2024). "The research demonstrates its role in promoting lung adenocarcinoma development both in vitro and in vivo, suggesting that a TMEM176B inhibitor or neutralising antibody could be investigated for targeted therapy." (PMID 39001509, 2024). "Notably, TMEM176B exhibited relatively lower expression in lung adenocarcinoma cell lines, specifically PC9 and A549, when compared with monocyte cell lines such as THP-1 and U-937." (PMID 39001509, 2024). "This suggests that TMEM176B may play an important role in the development of lung adenocarcinoma." (PMID 39001509, 2024). "This process was carried out using two lung adenocarcinoma cell lines, PC9 and A549, both of which displayed low TMEM176B expression levels." (PMID 39001509, 2024).
spinal cord injury (2 papers, 2020 to 2024). Penetrating and non-penetrating injuries to the spinal cord resulting from traumatic external forces (e.g., WOUNDS, GUNSHOT; WHIPLASH INJURIES; etc.). "It has been suggested that TMEM176A and TMEM176B inhibit the maturation and activation of dendritic cells in chronic spinal cord injury and that TMEM176B impairs IL-1β secretion and reduces CD8+ T cell-dependent antitumor immunity." (PMID 39684780, 2024). "TMEM176A and TMEM176B, which were suggested to inhibit DC maturation in chronic spinal cord injury, were expressed in three subtypes of monocytes." (PMID 33603736, 2020).
thymic lymphoma (2 papers, 2019 to 2021). "Genetic or pharmacological inhibition of Tmem176B in the immune microenvironment improved survival in three syngeneic murine cancer models: MC38 (colon), LL/2 (lung), and EG7 (thymic lymphoma)." (PMID 34943938, 2021). "Accordingly, Tmem176b−/− mice inoculated with MC38 (colon), LL/2 (LLC1; lung), or EG7 (thymic lymphoma) cell lines showed higher survival and reduced tumor growth compared with WT mice." (PMID 31085177, 2019).